SPP1 (secreted phosphoprotein 1)
Diseases named in the same sentence as SPP1 in open-access papers (continued):
Sharing a sentence is not in itself a finding about the gene and the disease.
tumor (continued). "Using single-cell RNA sequencing (scRNA-seq) analysis from public database, patient-derived organoid models, and in vivo mouse models, we demonstrated that IGLC3- tumor cells secreted TGF-β to polarize M0 macrophages into an SPP1+, M2-like phenotype." (PMID 41993204, 2026). "By contrast, the interaction between bone metastatic PC tumor cells and SPP1+ TAMs was mediated by the macrophage migration inhibitory factor (MIF) signaling pathway." (PMID 41362730, 2026). "These SPP1+ macrophages enhanced tumor cell proliferation, stemness, and migration via CD44-Wnt-BTF3 signaling pathway." (PMID 41993204, 2026). "We further identify a dynamic transition in the SELENOP+/SPP1+ macrophage populations as tumor metastasis, driven by increased hypoxia malignant epithelial cells through VEGFA-EPHB2 signaling." (PMID 41526347, 2026). "Single-cell analysis revealed that FASN and ACACA were predominantly expressed in tumor cells, while SPP1 was enriched in macrophages/monocytes." (PMID 42198359, 2026). "Cell communication analysis revealed extensive interactions between TRMs and other cell types, including CXCL/MIF and notably upregulated SPP1 signalling in tumour tissues." (PMID 42210511, 2026). "Monocytes were predominantly localized in proximity to tumor cells and exhibited activation of signaling pathways such as SPP1 and ICAM." (PMID 42099775, 2026). "TAMs facilitate tumor invasion, metastasis and immune evasion through secreted phosphoprotein 1 (SPP1) and interaction with the integrin family/CD44 axis in CAFs." (PMID 42156717, 2026). "Functional experiments confirmed that SPP1 promoted M2 macrophage polarization, enhanced immunosuppressive cytokine expression, and facilitated tumor progression through immune microenvironment remodeling." (PMID 41731467, 2026). "Spatial annotation and enrichment analyses using HALLMARK revealed gene set signatures of interferon and EMT present in cell clusters with SPP1 expression in both the primary tumor and lung metastases." (PMID 42174609, 2026). "This defined SPP1-TWIST1-SPON2 signaling circuit is pivotal in shaping the tumor microenvironment and promoting CRC PM progression." (PMID 41933135, 2026). "The increased prevalence of SPP1 + macrophages within the tumor microenvironment was correlated with inferior overall survival." (PMID 41869451, 2026). "In summary, the spatial transcriptomics and immunofluorescence results indicate that SPP1+ macrophages are enriched in tumor regions, potentially contributing to the hypoxia and glycolysis characteristics of the CRC TME." (PMID 40092488, 2025). "They discovered that the Slug(Snail family transcriptional repressor 2, SNAI2) transcription factor promotes tumor invasiveness and metastasis by directly regulating SPP1 expression." (PMID 41391064, 2025). "This review provides a comprehensive synthesis of the latest findings on SPP1+ macrophages, highlighting their roles in tumour progression, immune suppression, tissue remodelling, and fibrosis." (PMID 40395129, 2025). "For instance, CellChat analysis identified SPP1‐CD44 interactions between tumor cells and T cells, with SPP1 expression in malignant cells negatively correlating with T cell proliferation scores." (PMID 40062730, 2025). "SPP1+ TAM, located within the tumor core, cooperated with cancer-associated fibroblasts to induce extracellular matrix formation, thereby promoting HCC tumorigenesis." (PMID 40230843, 2025). "For example, SPP1+ macrophages and other subpopulations have been shown to foster immunosuppressive states in various tumours." (PMID 40988131, 2025). "These SEs showed strong correlations with key genes involved in immunosuppression and tumor progression, including SPP1, RAC1, CTSC, and SMS." (PMID 40725473, 2025).
tumor (continued). "In vivo experiments demonstrated that overexpression of SPP1 in ENO1-KO cells increased tumor volume and weight compared to ENO1-KO tumors (Additional file3P-R) and reduced the abundance of CD8+ T cells, IFN-γ+ CD8+ T cells, and GZMB+ CD8+ T cells." (PMID 40665335, 2025). "Several studies have shown that targeted blockade of SPP1 can inhibit tumor progression and metastasis." (PMID 40092488, 2025). "Elevated levels of circulating and tumor-derived SPP1 have been correlated with aggressive clinical features in HCC, including vascular invasion and metastasis." (PMID 41225975, 2025). "SPP1 emerged as a central mediator of cell–cell crosstalk in the tumor microenvironment, with especially high signaling activity between macrophages and various immune cells (monocytes, plasma B cells, T/NK cells, DCs)." (PMID 41268553, 2025). "The top expressed genes in SPP1+ TAMs include resistance-related genes and those involved in angiogenesis and tumor metabolism." (PMID 41341850, 2025). "SPP1 is widely expressed in many immunocytes and tumor cells, and has a prominent role in tumor development and immune response." (PMID 40303328, 2025). "These tumor cells reside near hypoxic tumor cores and are surrounded by a different set of immune cells such as SPP1+ macrophages and CD161+ CD8 T cells." (PMID 41450739, 2025). "In this review, we focus on recent advances in understanding the differentiation of SPP1 macrophages in hypoxic tumor microenvironment and the role of SPP1+ macrophages in immunosuppression and their therapeutic implications in cancer." (PMID 41425545, 2025). "In the tumor microenvironment (TME), macrophages are divided into two main subsets: C1Q+ and SPP1+ tumor-associated macrophages (TAMs), as well as two secondary subsets: FCN1+ and CCL18+ TAMs." (PMID 40034694, 2025). "We found that macrophages, which served as the source cells of tumor, showing stronger interaction strength with other cell types, especially fibroblasts and hepatocytes, and the SPP1, PTN, CCL, TGFB1 and PLAU pathways were more enriched in tumor regions." (PMID 40230843, 2025). "In the pro-tumor M1 module, SPP1/C1QC+ macrophages were at the top, primarily mediating varying degrees of CD8+T cell exhaustion, highlighting the central role of macrophage-T cell interactions in immune dysfunction." (PMID 40740771, 2025). "In a gene-level analysis, this pattern was consistent with the accumulation of Cd74+ and Cxcl9+ macrophages at the tumor edges and Spp1+ macrophages clustering toward the necrotic center." (PMID 41176316, 2025). "We observed that CAFs mainly existed in tumor regions, especially in tumor core region (58%), which is consistent with the observation on SPP1+ TAMs." (PMID 40230843, 2025). "Within the oncogenic context, SPP1 is widely recognized for its involvement in tumor progression, invasion, metastasis, and the reprogramming of the TME." (PMID 41031219, 2025). "Liver-resident Kupffer cells showed progressive loss of the core transcription factors SPIC and MAFB, suggesting a potential transition into SPP1+ TAMs under tumor pressure." (PMID 40725473, 2025). "A significant study focusing on FAP+ fibroblasts identified tumor-specific macrophages that were highly associated with FAP+ fibroblasts, namely SPP1+ TAMs." (PMID 40191203, 2025). "The results of the plate cloning formation demonstrated that the SPP1 OE Co-cultured CM group significantly increased the number of tumor cell clones." (PMID 40303328, 2025). "Using the GSVA algorithm, SPP1+ macrophages were found to be significantly increased in tumor tissues, while FOLR2+ macrophages were enriched in adjacent normal tissues." (PMID 40666097, 2025). "To overcome the heterogeneity of TAMs, VSIG4 and SPP1 were simultaneously inhibited and we found a synergic anti-tumor effect against ATC, highlighting targeting VSIG4-SPP1 axis as an emerging target for cancer immunotherapy." (PMID 39920772, 2025).
tumor (continued). "Lastly, a substantial upregulation of secreted phosphoprotein 1 (SPP1) has been observed in the tumor epithelial cells of ICC." (PMID 40070825, 2025). "In tumor tissues, SPP1+ macrophages engage in close crosstalk with FAP+ CAFs through specific signaling pathways, resulting in the immunosuppressive niche formation." (PMID 41425545, 2025). "Among them, SPP1+ TAMs have emerged as key players, with mounting evidence pointing to their involvement in tumour development, immune evasion, and resistance to therapy." (PMID 40395129, 2025). "The ability of SPP1+ TAMs to interact with fibroblasts and vasculature suggests a strong role in extracellular matrix remodeling and promoting angiogenesis in tumor settings." (PMID 40047497, 2025). "A study on NSCLC identified SPP1+ TAMs engaging with COL11A1‐expressing CAFs at the tumour boundaries, promoting collagen deposition and extracellular matrix remodelling." (PMID 40395129, 2025). "Specifically, patients with tumours exhibiting high expression of ECM‐related (SPP1 and MUC5B) and complete active related genes (CFB and CCL20) in either the epithelial or macrophage compartment had significantly shorter disease‐free survival (DFS)." (PMID 40847563, 2025). "Clinically, elevated SPP1 expression correlated with advanced tumor grade, progressive clinical stage, and poor prognosis in HNSCC patients." (PMID 41293726, 2025). "Because the majority of single‐cell transcriptomic studies have so far focused on cancer, macrophage subpopulations expressing high levels of SPP1 have been predominantly identified and characterised in tumours (see “SPP1 Macrophages in Cancer” chapter)." (PMID 40395129, 2025). "Specially, SPP1+ TAMs and STMN1+ TAMs were enriched in tumor core region, and SPP1+ TAMs showed the highest RO/E value of 4.74." (PMID 40230843, 2025). "Nanoparticle systems, such as CANDI460, have shown success in targeting SPP1 to inhibit tumor growth." (PMID 41221295, 2025). "Specifically, enteric glial cells within the tumour secrete IL‐6, which induces infiltrating monocytes to differentiate into SPP1‐expressing TAMs." (PMID 40395129, 2025). "Our results suggest that OCDMs inhibit CXCL9:SPP1 macrophage polarity and promote the transformation of macrophages into pro‐tumor macrophages." (PMID 40056029, 2025). "ACTM-838 converts human macrophages to an anti-tumor antigen presenting phenotype with reduced SPP1 expression in vitro." (PMID 41048107, 2025). "Given the pivotal role of SPP1 in promoting tumor progression through multiple mechanisms, directly targeting SPP1 itself represents a promising therapeutic strategy." (PMID 41391064, 2025). "SPP1 TAMs are pro-angiogenic, and their presence in tumors correlates with poorer survival, due in part to increased tumor vasculature and reduced immune infiltration." (PMID 41415295, 2025). "SPP1+ TAMs are enriched in tumor tissues compared with normal liver, and their increased abundance is linked to worse overall survival as well as resistance to ICB therapy in HCC." (PMID 41225975, 2025). "A recent study classified TAMs into pro-tumor and anti-tumor subsets based on the ratio of SPP1 and CXCL9." (PMID 39858015, 2025). "SPP1 plays multiple roles within a tumor, depending on the cell type, including enhancing M2-like macrophage infiltration." (PMID 40176808, 2025). "In aggressive cancers, VSIG4 blockade combined with SPP1 inhibition synergistically enhanced anti-tumor immunity by remodeling the TME and restoring CD8+ T cell function." (PMID 41425545, 2025). "This revitalization was characterized by reduced fractions of CCL18+ and SPP1+ macrophages alongside antitumor phenotypic remodeling of tumor-infiltrating macrophages and CD8+ T cells." (PMID 41409288, 2025). "They showed that increased SPP1 promotes tumor growth and prevents cell death by activating the NF-κB pathway." (PMID 41391064, 2025).
tumor (continued). "We will here discuss recent advances in understanding the differentiation of SPP1 macrophages in hypoxic tumor environment and the role of SPP1+ macrophages in immunosuppression and their therapeutic implications in cancer." (PMID 41425545, 2025). "Despite this heterogeneity, SPP1+ TAMs consistently contribute to tumour progression through shared features such as immunosuppression, extracellular matrix remodelling, and metabolic reprogramming." (PMID 40395129, 2025). "The presence of SPP1+ TAMs has been reported across various cancer types, often exhibiting context‐dependent functional roles shaped by the tumour microenvironment." (PMID 40395129, 2025). "Functional enrichment analysis revealed that SPP1+ Mac was significantly involved in cellular signaling and vascular development, highlighting their role in promoting tumor angiogenesis through enhanced pro‐angiogenic signaling." (PMID 40552583, 2025). "Gene expression patterns indicated SPP1 concentration in the non-tumor area, specifically within the region previously identified as containing macrophages." (PMID 39862439, 2025). "CellPhoneDB-based analyses predicted strong ligand–receptor interactions between CAFEndMT and tumor-associated macrophages (TAMs); in NicheNet analyses, CAFEndMT CD44 and TAM SPP1 (osteopontin; OPN)—an EndMT-inducing factor —ranked among the top interactions." (PMID 41154806, 2025). "A high proportion of SPP1+ macrophages was associated with genome instability and mutation (DNA mismatch repair deficiency, high levels of microsatellite instability, and high tumor mutation burden) in CRC, indicating that they could benefit from immunotherapy." (PMID 40092488, 2025). "A key outcome of this remodeling is the recruitment and activation of SPP1+ macrophages, which establish an immunosuppressive shield that protects the tumor from immune attack and promotes the angiogenesis required for its sustained growth." (PMID 41374989, 2025). "For example, ECM-myCAF, IFNαβ-myCAF, and TGFβ-myCAF clusters co-localize with immune cells such as TREM2+ tumor-associated macrophages (TAM) and SPP1+ TAM within the tumor bed, while Detox-iCAF co-localizes with FOLR2+ TAM in immuno-protective niches." (PMID 40890855, 2025). "The interaction between MDK‐high tumor cells and SPP1+ macrophages has been identified as the key mechanism contributing to the immunosuppressive TME." (PMID 41176774, 2025). "In contrast, anti-inflammatory Spp1+/Arg1+ macrophages, devoid of immunostimulatory functions, cluster near necrotic cores, underscoring the significance of the “functional tumor geography”." (PMID 41176316, 2025). "Recent research has highlighted that the CXCL9:SPP1 (CS) polarity dictates the anti-tumor or pro-tumor phenotype of TAMs." (PMID 40230843, 2025). "Hypoxic tumor regions, enriched in SPP1+ macrophages, foster an immunosuppressive and tissue-repairing microenvironment, which impairs RT efficacy." (PMID 41221295, 2025). "Building upon the established prognostic significance of eCAFs and SPP1+ macrophages, we performed systematic quantification of their temporal-spatial distribution patterns across tumor stages and histological differentiation grades." (PMID 40657391, 2025). "A critical insight from advanced single-cell RNA sequencing and spatial transcriptomics is that SPP1+ TAMs are also frequently enriched at the tumor–stroma interface, particularly at the invasive margin." (PMID 41425545, 2025). "Specifically, SPP1, as a potent chemokine for macrophages, can recruit TAMs from peripheral blood monocytes to the tumor microenvironment and promote M2 like activation of TAMs in this environment." (PMID 41384115, 2025). "The results of mIF showed that in both LM and PT lesions, SPP1+ macrophages were likely close to CK19‐positive tumor cells spatially." (PMID 41176774, 2025).
tumor (continued). "Within the TME, factors such as hypoxia, and interaction with tumor cells, fibroblasts and other immune cells polarize these cells toward an SPP1-expressing phenotype." (PMID 41425545, 2025). "mCAFs also show spatial colocalization with immune cells (e.g., SPP1+ macrophages, Treg cells), together forming an immunosuppressive niche that enhances tumor immune evasion." (PMID 41514658, 2025). "Differential expression marker analysis revealed that Macs/Mono S7 cells specifically expressed SPP1 and TREM1, indicating similarity to SPP1+ tumor‐associated macrophages (TAMs)." (PMID 40432877, 2025). "In primary NBs, we detected neuroblast-derived paracrine signaling through MK and SPP1, factors that drive angiogenesis and tumor progression." (PMID 41279557, 2025). "Overall, the luminal-associated transcriptional programs (FOXA1-EHF-ITGB4) and its downstream ECM-receptor interaction pathway (SPP1, CD44, ITGB4) play a crucial role in IMA, influencing its immunity and tumor risk." (PMID 39584073, 2025). "The intratumoral cellular programs of SPP1+ TAMs, including promoting angiogenesis, enhancing tumor cell invasion, and resisting immune checkpoint blockade (ICB) therapy, have been reported." (PMID 40666097, 2025). "SPP1, a known mediator of tumor microenvironment interactions, has been shown to be highly expressed in multiple cancers, including breast, lung, and colorectal cancers, where it enhances tumor growth, invasion, and immune evasion." (PMID 41465316, 2025). "The SPP1+ macrophage cluster also expressed HMOX1, which has been shown to play a role in the immunosuppressive program of tumor-associated macrophages (TAM)." (PMID 40647416, 2025). "Statistical analysis demonstrated significantly elevated SPP1+BCL2A1+ TAMs scores in tumor tissues (p < 0.0001), establishing this newly identified TAM subtype as an HCC-enriched immune subset." (PMID 41225975, 2025). "Their study demonstrated that SPP1‐secreting tumour cells interacts with CD44‐expressing exhausted CD8+ T cells in situ, thereby reshaping the immune microenvironment and driving primary resistance." (PMID 40677104, 2025). "Studies have confirmed that BET inhibitors and cytarabine can suppress SPP1 transcription, while Entrectinib directly binds to SPP1 and reduces its expression, resulting in synergistic anti-tumor effects." (PMID 41384115, 2025). "Recent research found that HCC patients who do not respond to anti-PD-1 treatment exhibit an immune barrier near the tumor boundary, composed of CAFs and SPP1+ macrophages, which blocks the infiltration of cytotoxic T cells into the tumor." (PMID 40051497, 2025). "Of note, Scupa analysis revealed SPP1+ macrophages polarized to Mac-e state, a M2-like polarization state, suggesting its pro-tumor roles." (PMID 39999031, 2025). "Collectively, these findings underscore SPP1+ macrophages as critical drivers of tumor development in GI cancers." (PMID 41316282, 2025). "The observed increase in SPP1+ TAMs in tumor-bearing livers reinforces the biological plausibility of computational predictions." (PMID 40725473, 2025). "Upregulation of hub gene SPP1, and its corresponding protein in both pleomorphic tumour cells and TAMs (predominantly comprising osteoclast-like giant cells) was shown for Case One." (PMID 40790295, 2025). "In vivo experiments also showed the SPP1 expression was significantly downregulated in ENO1-KO tumor tissues." (PMID 40665335, 2025). "In young 67NR tumor-bearing mice, calcitriol increased Rora and Gata3 expression, while tacalcitol decreased Spp1." (PMID 40894304, 2025). "It has been reported that elevated levels of SPP1 in tumor cells are correlated with a poor prognosis in NSCLC." (PMID 40761262, 2025). "The results showed that SPP1 inhibitory can significantly inhibited the tumor growth and tumor weight." (PMID 40665335, 2025).